CARD9 (caspase recruitment domain family member 9)
Diseases named in the same sentence as CARD9 in open-access papers (continued):
Sharing a sentence is not in itself a finding about the gene and the disease.
Salmonella Infections (3 papers, 2016 to 2023). Infections with bacteria of the genus SALMONELLA. "In the context of Salmonella infection, it has also been reported that CARD9 negatively regulates IL-1β by fine-tuning pro-IL-1β expression, SYK-mediated NLRP3 activation and repressing inflammasome-associated caspase-8 activity." (PMID 37528097, 2023). "Similar to the present findings, CARD9−/− mice exhibit increased splenic IL-1β expressions following systemic Salmonella infection." (PMID 34209576, 2021). "To test this hypothesis we investigated whether Salmonella infection alters CARD9 protein expression and thereby potentially alters the resulting level of inflammasome activation." (PMID 27670879, 2016). "Nigericin stimulation does not trigger CARD9 downregulation supporting our hypothesis that the regulation of CARD9 expression in macrophages is specifically downregulated on Salmonella infection possibly to maximize the host inflammasome response to infection." (PMID 27670879, 2016).
acute pneumonia (2 papers, 2010 to 2015). "Overall, these results suggest that the attenuation of influenza pneumonia by Card9 deficiency was likely attributable to the reduced cytokine/chemokine production by pulmonary DCs through the Syk-CARD9 pathway in response to IFV." (PMID 26627732, 2015). "We found that influenza pneumonia was dramatically attenuated in Card9-deficient mice, which showed improved mortality with reduced inflammatory cytokines and chemokines in the infected lungs." (PMID 26627732, 2015). "Given the pathological similarity between the mouse intratracheal infection model and influenza-associated ARDS in human, we postulate that the CARD9 pathway contributes to the exacerbation of human influenza pneumonia." (PMID 26627732, 2015). "Collectively, the loss of CARD9 attenuated severe influenza pneumonia and improved host mortality." (PMID 26627732, 2015). "Our results showed that the CARD9 pathway was involved in fatal influenza pneumonia mediated by inflammatory cytokine/chemokine production, whereas it was dispensable for type-I interferon production as well as the development of anti-viral acquired immunity." (PMID 26627732, 2015). "We have shown that CARD9-mediated activation of the innate immune system exacerbates influenza pneumonia in mice." (PMID 26627732, 2015). "In conclusion, CARD9-mediated innate immune activation in pulmonary DCs acts to exacerbate severe influenza pneumonia, but is dispensable for host protection against IFV." (PMID 26627732, 2015). "However, the roles of CARD9 in influenza pneumonia, as well as in protection against IFV are yet to be elucidated." (PMID 26627732, 2015). "In this study, we focused on CARD9, a signaling adaptor known to regulate innate immune activation through multiple innate sensor proteins and investigated its role in anti-IFV defense and lung pathogenesis in a mouse model recapitulating severe influenza pneumonia with ARDS." (PMID 26627732, 2015).
B-Cell CLL (2 papers, 2017 to 2020). "Instead, it recruits an ITAM-linked FcRγ, which initiates signaling through Syk and likely the Caspase recruitment domain family member 9/B-Cell CLL/lymphoma 10/Mucosa-associated lymphoid tissue lymphoma translocation protein 1 (CARD9/BCL10/MALT1) complex." (PMID 28640912, 2017). "The short tail recruits an ITAM-linked FcRγ, which activates signaling through Syk and possibly the Caspase recruitment domain family member 9/B-Cell CLL/lymphoma 10/Mucosa-associated lymphoid tissue lymphoma translocation protein 1 (CARD9/BCL10/MALT1) complex." (PMID 33628745, 2020).
Candidemia (2 papers, 2021 to 2025). A form of invasive candidiasis where species of CANDIDA are present in the blood. "Using a standard high-dose model of candidemia, the Y91HKI mouse phenocopies the Card9–/– mouse with respect to acuity, morbidity, mortality, and tissue fungal burden, relative to WT mice." (PMID 40424070, 2025).
cognitive decline (2 papers, 2023 to 2026). "We specifically demonstrate that CARD9 deletion in 5xFAD mice leads to impaired control of Aβ, worsened cognitive decline, and aberrant microglial activation." (PMID 37276426, 2023).
cystic fibrosis (2 papers, 2021 to 2025). Autosomal recessive disorder caused by pathogenic variants in the CFTR gene (cystic fibrosis transmembrane conductance regulator), which encodes a chloride and bicarbonate channel expressed in epithelial cells, and follow the diagnosis criteria. "The fungus is frequently isolated from individuals with structural lung disease or immunological defects, including cystic fibrosis, hematological malignancies, CARD9 deficiency, or those receiving immunosuppressive therapy." (PMID 40725051, 2025). "First, we examined the clinical and epidemiological background of E. dermatitidis, with particular focus on its involvement in cystic fibrosis and CARD9 deficiency, as well as central nervous system, ocular, and systemic infections." (PMID 40725051, 2025).
diabetic nephropathy (2 papers, 2022). "In summary, our study found that A&P is effective in reducing renal pathological damage and improving renal function and inflammation in diabetic nephropathy by a mechanism mainly related to the inhibition of the Mincle/Card9/NFκB signaling pathway." (PMID 35057768, 2022). "In addition, CARD9 staining in renal biopsies with minimal change disease (MCD), focal segmental glomerulosclerosis (FSGS), diabetic nephropathy (DN), and membranoproliferative glomerulonephritis (MPGN) was negative while that of Henoch–Schonlein purpura nephritis (HSPN) was positive." (PMID 35733381, 2022).
eosinophilia (2 papers, 2020 to 2022). "Furthermore, high levels of serum IgE and eosinophilia were also a feature in all patients with CARD9 deficiency and invasive fungal invasion, but the link of these responses with the absence of CARD9 remains unexplained so far." (PMID 33343578, 2020).
Granuloma (2 papers, 2016 to 2022). A compact, organized collection of mature mononuclear phagocytes, which may be but is not necessarily accompanied by accessory features such as necrosis. "We therefore first used histological analysis, which revealed large granulomas with neutrophils surrounded by lymphocytes and histiocytes and significantly increased C. cassiicola invasion within granulomas of Card9–/– mice." (PMID 36377664, 2022). "The occurrence of granuloma is reduced, but not completely eliminated in the Card9 KO mice, indicating that T cells also play a significant role in the immune responses to the bare aggregates and single cells." (PMID 27786170, 2016).
influenza (2 papers, 2015 to 2018). An acute viral infection of the respiratory tract, occurring in isolated cases, in epidemics, or in pandemics; it is caused by serologically different strains of viruses (influenzaviruses) designated A, B, and C, has a 3-day incubation period, and usually lasts for 3 to 10 days. "In this study, we demonstrate a role for CARD9-mediated innate activation in influenza pathogenesis and immunity." (PMID 26627732, 2015). "Several lines of evidence have implied a role for CARD9-mediated innate activation pathways in influenza pathogenesis and immunity." (PMID 26627732, 2015). "Thus, it is likely that the Syk-CARD9 pathway controls detrimental cytokine production by pulmonary DCs upon acute influenza infection." (PMID 26627732, 2015).
ischemia (2 papers, 2023 to 2024). A hypoperfusion of the BLOOD through an organ or tissue caused by a PATHOLOGIC CONSTRICTION or obstruction of its BLOOD VESSELS, or an absence of BLOOD CIRCULATION. "Meanwhile, CARD9 expression has also been demonstrated to increase in H9C2 cells and neonatal rat primary cardiomyocytes exposed to hypoxia and hypoxia/reoxygenation, affording CARD9's protection of myocardium against ischemia/reperfusion injury." (PMID 39118286, 2024). "The data indicate that CARD9 signaling plays an important role in PM exposure-induced ROS production and impaired limb recovery following ischemia in mice." (PMID 36860276, 2023).
Listeria monocytogenes infection (2 papers, 2019 to 2021). "In addition, CARD9−/− mice exhibit an early increase in IFN-γ blood levels in response to Listeria monocytogenes infection." (PMID 34209576, 2021).
lupus nephritis (2 papers, 2012 to 2023). Glomerulonephritis in the context of systemic lupus erythematosus. "Murine kidney showed higher DAP-12, Syk, Card-9 and Dectin-1 mRNA expression during the progression of lupus nephritis." (PMID 22949850, 2012). "In addition, in a mouse study, Card-9 mRNA expression was increased in the murine kidney during lupus nephritis progression." (PMID 36782298, 2023).
lymphoma (2 papers, 2022 to 2024). A malignant (clonal) proliferation of B- lymphocytes or T- lymphocytes which involves the lymph nodes, bone marrow and/or extranodal sites. "To complement our findings, we examined CARD9 protein levels in a series of RS tissue specimens and different lymphoma entities." (PMID 35158799, 2022). "In particular, we detected CARD9 expression in the lymphoma cells from 53% of the RS cases, whereas de novo DLBCL and DLBCL arising through transformation of lymphomas other than CLL only rarely exhibited CARD9." (PMID 35158799, 2022). "We also showed immunostaining for CARD9 in 53% of cases analyzed in a series of RS tissue specimens, whereas other lymphomas rarely show CARD9 expression." (PMID 35158799, 2022). "In contrast, the parent RS DLBCL from which U-RT1 was established contained sheets of CARD9-positive lymphoma cells." (PMID 35158799, 2022). "This is the first report of an ectopic expression of CARD9 in an aggressive lymphoma." (PMID 35158799, 2022). "We also tested 17 DLBCLs that had arisen from lymphomas other than CLL/SLL, and found CARD9 expression in 2 of these cases." (PMID 35158799, 2022). "We have shown the expression of CARD9 in a subset of RS cases, in the RS model system U-RT1, as well as in the parent lymphoma of the cell line." (PMID 35158799, 2022). "We demonstrated the expression of CARD9 in the RS model system U-RT1, as well as in the parent lymphoma of the cell line." (PMID 35158799, 2022).
myocardial infarct (2 papers, 2018 to 2021). "They further elucidated that CARD9 deletion exacerbates myocardial infarction via autophagic dysregulation, indicating that autophagic activity is maintained during myocardial infarction via sequestration of Rubicon by CARD9." (PMID 35083223, 2021). "Our study indicated that neutrophil infiltration following myocardial infarction is at least partially regulated by CARD9." (PMID 29940016, 2018).
pneumococcal infection (2 papers, 2024 to 2025). Infections with bacteria of the species streptococcus pneumoniae. "CARD9-deficient mice showed reduced specific-immune cell infiltration in the lungs compared to the wild type in response to pneumococcal infection; specifically, the number of neutrophils was significantly reduced compared to the wild type, but the number of macrophages was not altered." (PMID 38473845, 2024). "Furthermore, in Streptococcus pneumoniae infection, another Gram-positive bacterium, CARD9 KO mice exhibit decreased neutrophil numbers due to reduced chemokine production." (PMID 40574842, 2025).
Pneumocystis infection (2 papers, 2024 to 2025). "However, in other studies, a CARD9 deficiency resulted in impaired phagocytosis and killing ability against unopsonized C. albicans, C. neoformans, and Pneumocystis infections." (PMID 38473845, 2024). "Previously, we have reported that in immunocompetent Card9−/− animals after 20 days of Pneumocystis infection, we noted approximately a 3-fold increase in organism burden compared with WT animals." (PMID 39745390, 2025).
psoriasis (2 papers, 2017 to 2025). An autoimmune condition characterized by red, well-delineated plaques with silvery scales that are usually on the extensor surfaces and scalp. "The observed association between psoriasis and IBD is well documented and supported by shared genetic and immunologic pathways, including polymorphisms in IL23R, NOD2, and CARD9 genes." (PMID 40746559, 2025).
renal cell carcinoma (2 papers, 2018). "This study showed that CARD9 induced a multiprotein complex with BCL10 proteins, which recruited TRAFs in pVHL-deficient renal cell carcinomas (RCC)." (PMID 29352133, 2018).
tinea (2 papers, 2015 to 2024). "Deficiency in caspase recruitment domain-containing protein 9 (CARD9) has also been shown to be associated with more severe presentations of tinea infections." (PMID 38667966, 2024). "This spectrum ranges from the benign and localized tinea on the one hand, where the host’s defenses appear to be intact, to the life-threatening systemic infections on the other, as seen in CARD9-deficient or severely immunocompromised patients [e.g., cirrhotic patients]." (PMID 26300867, 2015).
uveitis (2 papers, 2018). An inflammatory process affecting a part of or the entire uvea. "For its specific contribution on the pathogenesis of uveitis, SYK/CARD9 signaling axis participates in the pathogenesis of autoimmune eye diseases, including ocular inflammatory disorders, uveitis, and dry eye disease." (PMID 30349554, 2018). "During experimental uveitis, Mincle-mediated activation of CARD9 is required for the recruitment of pathogenic Th1 and Th17 cells, and it was later shown that fungal antigens could exacerbate the development of this disease and this occurred via Dectin-2-CARD9 signaling." (PMID 30127791, 2018).
abscesses (1 paper, 2021). "The difference was most prominent in the kidneys (>200-fold), which also manifested in small abscesses in both the Syk−/− and CARD9−/− backgrounds." (PMID 34465030, 2021).
amyloidosis (1 paper, 2023). A disorder characterized by the localized or diffuse accumulation of amyloid protein in various anatomic sites. "Given the increased neuronal loss and amyloidosis observed in CARD9-deficient 5xFAD mice, we next sought to determine whether Card9−/−5xFAD mice also display deficits in learning and memory." (PMID 37276426, 2023).
aortic atherosclerosis (1 paper, 2023). A atherosclerosis that involves the aorta. "Given the marked increase in aortic atherosclerosis in the absence of hematopoietic Card9 and the colocalization between Card9+ macrophages and lipid-rich areas in both mouse and human plaques, we then focused on the role of Card9 in macrophage foam cell formation." (PMID 37528097, 2023).
Behcet disease (1 paper, 2022). A chronic, relapsing, multisystemic vasculitis characterized by mucocutaneous lesions, as well as articular, vascular, ocular and central nervous system manifestations. "Later, the CARD9 gene haplotype CGCCA (rs4077515, rs11145769, rs59902911, rs9411205, rs4073153) is reported to be a protective factor for primary immune thrombocytopenia (ITP), Behcet’s disease (BD) and ankylosing spondylitis (AS) from Haplotype analysis and a genome-wide association study (GWAS)." (PMID 35432375, 2022).
breast carcinoma (1 paper, 2022). "To check whether the genes which showed hypomethylation upon drug treatment were hypo or hypermethylated in breast cancer patients, we checked for the methylation status of the genes and found CARD9 and NELFB to be hypermethylated in breast cancer samples using SMARTapp." (PMID 36474139, 2022).
chromoblastomycosis (1 paper, 2022). "This is, to our knowledge, the first report that links chromoblastomycosis to CARD9 mutation, which challenges our previous perspective that chromoblastomycosis patients are mostly immunocompetent." (PMID 36159827, 2022). "In this study we report, for the first time, a patient harboring the CARD9 mutation with chromoblastomycosis caused by Phialophora expanda, which is a fungus from the Phialophora verrucosa complex according to our previous phylogenetic studies." (PMID 36159827, 2022).
Coccidioides infection (1 paper, 2017). "Studies of signal transduction pathways reveal that MyD88 and caspase recruitment domain-containing protein 9 (Card9), two intracellular immune adaptors, are essential for the activation of protective Th17 response to Coccidioides infection." (PMID 28300772, 2017).
Cognitive impairment (1 paper, 2023). Abnormal cognition is characterized by deficits in thinking, reasoning, or remembering. "In addition, we find that CARD9 protects against cognitive impairment in 5xFAD mice." (PMID 37276426, 2023).
Cryptococcal meningitis (1 paper, 2024). Meningeal inflammation produced by cryptococcus neoformans, an encapsulated yeast that tends to infect individuals with acquired immunodeficiency syndrome and other immunocompromised states. "Although Card9 deficiency has not been associated with human cryptococcal meningitis, the experimental findings in the current report suggest the role of Card9 in antifungal host defense of the brain may not be limited to Candida sp." (PMID 38921420, 2024).
cystitis (1 paper, 2024). Inflammation of the urinary bladder. "Additionally, prior research has highlighted the role of the Nod-like and C-type lectin receptor pathways in triggering acute CYP-induced cystitis in mice through caspase recruitment domain-containing protein 9 (CARD9) signaling." (PMID 38997336, 2024).
fibrosis (1 paper, 2022). the formation of excess fibrous connective tissue in an organ or tissue in a reparative or reactive process. "The upregulation of cardiac CARD9 protein expression along with cardiac fibrosis and dysfunction was recently found in obese mice induced by high fat diet (HFD); however, these effects were blunted in CARD9-KO mice." (PMID 35173530, 2022).
follicular lymphoma (1 paper, 2022). Follicular lymphoma is a form of non-Hodgkin lymphoma characterized by a proliferation of B cells whose nodular structure of follicular architecture is preserved. "In this group, both CARD9-positive cases were DLBCLs that had progressed from a follicular lymphoma." (PMID 35158799, 2022).
gastric MALT lymphomas (1 paper, 2022). "In addition, gains of chromosomal material, including the chromosome 9q34 gene locus of CARD9, have been identified in a subset of gastric MALT lymphomas." (PMID 35158799, 2022). "In the context of neoplasia, CARD9 has been demonstrated in gastric MALT lymphoma." (PMID 35158799, 2022).
Hyperbilirubinemia (1 paper, 2014). An increased amount of bilirubin in the blood. "Genetic analysis of the frequency of minor allele of NOD2, CARD9, RAC1 and ATG16L1 polymorphisms in IF patients with conjugated hyperbilirubinemia (CB≥50 μmol/L)." (PMID 24465786, 2014). "Genetic analysis of the frequency of minor allele of NOD2, CARD9, RAC1 and ATG16L1 polymorphisms in IF patients with conjugated hyperbilirubinemia (CB≥100 μmol/L)." (PMID 24465786, 2014).
hypercoagulation (1 paper, 2025). "Card9–/– mice treated with clodronate developed hypercoagulation resulting in 50% of mice not surviving to day 4 p.i.." (PMID 40424070, 2025).
Impaired glucose tolerance (1 paper, 2026). An abnormal resistance to glucose, i.e., a reduction in the ability to maintain glucose levels in the blood stream within normal limits following oral or intravenous administration of glucose. "OGTT revealed impaired glucose tolerance, and ELISA demonstrated reduced serum insulin levels in Card9−/− mice." (PMID 41243316, 2026).
infarction (1 paper, 2023). A localised pathological necrosis of tissue resulting from obstruction of the blood supply usually by a thrombus, an embolus, or vascular torsion. "Subsequently, we assayed the protein levels of CARD9 in myocardium at different time following infarction and found that CARD9 expression was induced as early as 1 day, peaked on 3 days, and descended on 7 days post-MI." (PMID 37828006, 2023).
infection of the central nervous system (1 paper, 2024). "As infection of the central nervous system is the most serious and potentially fatal consequence of pulmonary cryptococcal disease, we also examined whether mutation of Card9 altered the rate of dissemination and fungal burden in the brain." (PMID 38921420, 2024).